HEPACAM2 (HEPACAM family member 2)
Description:
Required during prometaphase for centrosome maturation. Following poly-ADP-ribosylation (PARsylation) by TNKS, translocates from the Golgi apparatus to mitotic centrosomes and plays a key role in the formation of robust microtubules for prompt movement of chromosomes: anchors AKAP9/CG-NAP, a scaffold protein of the gamma-tubulin ring complex and promotes centrosome maturation.
Synonyms: MIKI; FLJ38683
Tractability: Antibody: UniProt predicts a signal peptide or a membrane-spanning region.
Gene: Protein-coding gene on chromosome 7 (93,188,534 to 93,226,559, reverse strand). Ensembl gene ENSG00000188175.
Subcellular location: Golgi apparatus membrane; Cytoplasm, cytoskeleton, spindle; Cytoplasm, cytoskeleton, microtubule organizing center, centrosome; Midbody
Subcellular location (Human Protein Atlas): Mitotic spindle; Vesicles; Nucleoplasm
Gene Ontology:
Molecular function: protein binding
Biological process: centrosome cycle
Cellular component: centrosome; Golgi apparatus; Golgi membrane; midbody; mitotic spindle; spindle
Genetic constraint (gnomAD): Loss-of-function variants: 34 observed, 38.23 expected, observed/expected ratio (o/e) 0.89, 90% interval 0.68 to 1.18. The upper end of that interval is the gene's LOEUF score, 1.18, which puts it in group 5 of 6, group 1 being the genes least tolerant of losing a copy. Missense variants: 453 observed, 515.33 expected, observed/expected ratio (o/e) 0.88, 90% interval 0.81 to 0.95. Synonymous variants: 173 observed, 191.08 expected, observed/expected ratio (o/e) 0.91, 90% interval 0.8 to 1.03.
Homologues: Orthologues: chimpanzee HEPACAM2 (99% identical), macaque HEPACAM2 (97% identical), rabbit HEPACAM2 (89% identical), dog HEPACAM2 (88% identical), guinea pig HEPACAM2 (86% identical), mouse Hepacam2 (85% identical), rat Hepacam2 (84% identical), pig HEPACAM2 (73% identical), tropical clawed frog hepacam2 (57% identical), zebrafish hepacam2 (35% identical). Paralogues in human: HEPACAM (20% identical), CEACAM1 (19% identical), CEACAM5 (18% identical), CEACAM6 (16% identical), PSG1 (16% identical), PSG8 (16% identical), PSG6 (16% identical), CEACAM8 (16% identical), PSG3 (16% identical), PSG4 (16% identical), PSG11 (15% identical), PSG7 (15% identical), and 12 more.
Diseases named in the same sentence as HEPACAM2 in open-access papers:
HEPACAM2 is named in the same sentence as 15 diseases in open-access papers, as found by Europe PMC text mining. Sharing a sentence is not in itself a finding about the gene and the disease. The quoted sentences say what the papers report.
adenoma (2 papers, 2010 to 2024). A neoplasm arising from the epithelium. "HEPACAM2 mRNA expression was significantly increased in microdissected adenomas when compared to normal gland, carcinomas and lymph node metastases." (PMID 20226097, 2010). "In the present study, we found an increased HEPACAM2 expression in adenomas when compared to normal gland." (PMID 20226097, 2010). "HEPACAM1 and 2 mRNA expression levels are therefore similar in adenomas, while carcinomas and metastases have decreased HEPACAM2 but not HEPACAM1 mRNA expression levels." (PMID 20226097, 2010).
mammary tumors (2 papers, 2010). "Furthermore, it can be speculated, whether HEPACAM2 plays a different role in malignancy and metastasis of canine mammary tumours since its transcriptional levels are different in carcinomas and their lymph node metastases when compared to HEPACAM1." (PMID 20226097, 2010).
colitis (1 paper, 2025). Inflammation of the colon. "Hepacam2 expression was further increased in ERAP1+/− colitis mice following sulfasalazine treatment, reinforcing its potential as a biomarker for UC subtypes and ERAP1-related immune modulation." (PMID 40977735, 2025). "Notably, mRNA expression levels of Anxa9 (p < 0.05), Atp2a1 (p < 0.001), and Hepacam2 (p < 0.01) were all significantly upregulated in ERAP1+/− colitis mice relative to WT colitis mice after sulfasalazine treatment, indicating its potential role in colitis pathogenesis and therapeutic response." (PMID 40977735, 2025). "Transcriptomic analysis via RNA sequencing revealed upregulation of genes implicated in colitis and colorectal cancer (CRC) progression, such as Anxa9, Atp2a1, and Hepacam2, in ERAP1+/− mice, regardless of sulfasalazine administration." (PMID 40977735, 2025).
gastric cancer (1 paper, 2024). A primary or metastatic malignant neoplasm involving the stomach. "Notably, UGT2B15, previously associated with pathogenesis and prognosis of gastric cancer and HEPACAM2, upregulated in patients with poor prognosis and linked to metastasis in various types of cancer, were highlighted." (PMID 39123475, 2024).
lymph node metastases (1 paper, 2010). "In contrast, carcinomas and lymph node metastases had a constant and marked decrease in HEPACAM2 expression levels." (PMID 20226097, 2010).
mammary carcinomas (1 paper, 2010). "HEPACAM2 transcription levels were decreased in mammary carcinomas but further analysis of the function and the expression pattern of the HEPACAM2 protein are needed to evaluate its role in normal mammary gland physiology and malignant transformation." (PMID 20226097, 2010).
metastatic carcinoma (1 paper, 2010). A carcinoma which has spread from the original site of growth to another anatomic site. "In contrast, metastatic carcinomas, intravascular tumour cells and lymph node metastases had HEPACAM 1 protein and mRNA expression levels similar to normal gland but decreased HEPACAM2 mRNA expression when compared to normal gland of the same dog." (PMID 20226097, 2010).
small cell lung carcinoma (1 paper, 2025). Small cell lung cancer (SCLC) is a highly aggressive malignant neoplasm, accounting for 10-15% of lung cancer cases, characterized byrapid growth, and early metastasis. "Research indicates that HEPACAM2 is highly expressed in small cell lung cancer." (PMID 41459538, 2025).
tumor (9 papers, 2010 to 2025). "We detected 5-fold down-regulation in the transcription of HEPACAM2, a gene encoding hepacam which is an immunoglobulin-like cell adhesion molecule purported to be a tumour suppressor." (PMID 24885874, 2014). "However, claudin-15 functions primarily as a pore forming protein, and HEPACAM2 is a purported tumor suppressor, thus reductions to their abundance likely would not increase epithelial permeability." (PMID 34147126, 2021). "HEPACAM family member 2 (HEPACAM2) is a paralog of Hepatocyte Cell Adhesion Molecule (HEPACAM), which is known to act as a tumor suppressor by promoting differentiation." (PMID 31337362, 2019). "HEPACAM2, ITLN1, LGALS2, MUC12, and NXPE1 presented a sequentially descending trend in expression with tumor progression." (PMID 29659199, 2018). "Following this, we performed a more detailed examination regarding the tumor cells and classified four tumor cell subtypes based on the expression levels of marker genes (C0 MUC5AC+ subtype, C1 NDUFAB1+ subtype, C2 SRGN+ subtype, C3 HEPACAM2+ subtype)." (PMID 40688093, 2025). "Notably, the heterogeneity of EPCs, particularly the identification of four distinct tumor cell subtypes (C0 MUC5AC+, C1 NDUFAB1+, C2 SRGN+, and C3 HEPACAM2+), highlighted the complexity of GC biology." (PMID 40688093, 2025).
cancer (5 papers, 2010 to 2025). A tumor composed of atypical neoplastic, often pleomorphic cells that invade other tissues. "Intriguingly, several genes showing positive correlation in gene bodies have been previously linked to cancer, including MUC15, HEPACAM2, CA10, NRG1 and RAB25 (Mitra, Cheng & Mills, 2012)." (PMID 32832275, 2020). "In contrast, 12 out of 13 carcinomas and 13 out of 13 lymph node metastases had decreased HEPACAM2 mRNA expression levels lower than 0.5 fold of the normal gland epithelium of the same dog." (PMID 20226097, 2010). "HEPACAM2 is another gene implicated in cancer that we could not find a direct ASCL1 association in the literature." (PMID 40257984, 2025).
infection (1 paper, 2014). The state of being infected such as from the introduction of a foreign agent such as serum, vaccine, antigenic substance or organism. "Within the locus we also identified host genes whose expression increased (Samd9l, Asns, Gpr85, and Tfpi2) or decreased (Pon1, Hepacam2, Tmem106b, and Pppr9a1) 2-fold (P < 0.05) 72 hours after infection with H5N1 IAV in D2, B6 or both mouse strains." (PMID 25418976, 2014).
HEPACAM2 also shares sentences with these, for which no sentence is quoted: colorectal cancer (1 paper); metabolic disease (1); myelodysplastic syndrome (1); myeloid leukemia (1).